CLRN3 (clarin 3)
Synonyms: TMEM12; USH3AL1; MGC32871
Tractability: Antibody: UniProt predicts a signal peptide or a membrane-spanning region. PROTAC: its protein half-life has been measured.
Gene: Protein-coding gene on chromosome 10 (127,877,841 to 127,892,947, reverse strand). Ensembl gene ENSG00000180745.
Subcellular location: Membrane
Gene Ontology:
Molecular function: protein binding
Biological process: sensory perception of sound
Cellular component: extracellular exosome; membrane
Genetic constraint (gnomAD): Loss-of-function variants: 9 observed, 13.46 expected, observed/expected ratio (o/e) 0.67, 90% interval 0.4 to 1.17. The upper end of that interval is the gene's LOEUF score, 1.17, which puts it in group 5 of 6, group 1 being the genes least tolerant of losing a copy. Missense variants: 228 observed, 225.62 expected, observed/expected ratio (o/e) 1.01, 90% interval 0.91 to 1.13. Synonymous variants: 93 observed, 98.2 expected, observed/expected ratio (o/e) 0.95, 90% interval 0.8 to 1.12.
Homologues: Orthologues: chimpanzee CLRN3 (98% identical), macaque CLRN3 (94% identical), dog CLRN3 (76% identical), rat Clrn3 (76% identical), rabbit CLRN3 (74% identical), mouse Clrn3 (73% identical), guinea pig CLRN3 (73% identical), pig CLRN3 (72% identical), tropical clawed frog clrn3 (44% identical), zebrafish clrn3 (32% identical), Caenorhabditis elegans Y67D8C.22 (19% identical), Drosophila melanogaster CG1103 (19% identical). Paralogues in human: CLRN2 (25% identical), CLRN1 (23% identical).
Diseases named in the same sentence as CLRN3 in open-access papers:
CLRN3 is named in the same sentence as 7 diseases in open-access papers, as found by Europe PMC text mining. Sharing a sentence is not in itself a finding about the gene and the disease. The quoted sentences say what the papers report.
gastric cancer (2 papers, 2015 to 2019). A primary or metastatic malignant neoplasm involving the stomach. "CLRN3 has been identified as a HNF4A transcriptional target in iPSC-derived hepatocytes, and CLDN18 has been confirmed as a GATA6 target in gastric cancer; therefore, we used these likely targets to test the regulatory potential of HNF4A and GATA6 in OE19 cells." (PMID 30962179, 2019). "In addition, we discovered some novel genes, such as TMEM184A, PSAPL1, KIAA1199, CLRN3 and FNDC1, which have not been reported in gastric cancer previously, and their roles in cancer remain unknown." (PMID 25928635, 2015).
colorectal cancer (1 paper, 2024). A primary or metastatic malignant neoplasm that affects the colon or rectum. "Importantly, CLRN3 was identified as a pivotal gene in the progression of colorectal cancer (CRC) and promoted the proliferation and advancement of CRC through both in vitro and in vivo experiments." (PMID 39199281, 2024). "Lastly, our study identified CLRN3 as a pivotal gene in the progression of colorectal cancer (CRC), demonstrating that CLRN3 promotes the proliferation and advancement of CRC through both in vitro and in vivo experiments." (PMID 39199281, 2024). "To delve deeper into the influence of CLRN3 on the progression of colorectal cancer (CRC) in vivo, we established a subcutaneous xenograft model in nude mice using HCT116 cell lines that had been genetically modified to either overexpress or knockdown CLRN3." (PMID 39199281, 2024).
tumor (2 papers, 2024 to 2025). "Liver- and tumor-associated markers, such as AADAC, CLRN3, GPC3, CD40, and ALB, were downregulated in LC4 cells compared to freshly isolated tumor core cells and parental tissues." (PMID 40431665, 2025). "CLRN3 expression levels in tumor and adjacent normal tissues were assessed using quantitative real-time polymerase chain reaction (qRT-PCR) and western blot." (PMID 39199281, 2024). "The findings revealed a marked elevation in the expression of CLRN3 within tumor specimens in comparison to their normal tissue counterparts, and this upsurge became more pronounced with advancing pathological stages." (PMID 39199281, 2024). "Our results indicated that CLRN3 overexpression significantly accelerated the growth of the subcutaneous xenograft tumors compared to those with the control vector, whereas the knockdown of CLRN3 effectively suppressed tumor growth in comparison to the control group." (PMID 39199281, 2024).
CLRN3 also shares sentences with these, for which no sentence is quoted: cancer (2 papers); cervical adenocarcinoma (1); neurological disease (1); Parkinson disease (1).